PRUNE2 (prune homolog 2 with BCH domain)
Diseases named in the same sentence as PRUNE2 in open-access papers (continued):
Sharing a sentence is not in itself a finding about the gene and the disease.
tumor (25 papers, 2009 to 2025). "High PRUNE2 levels are associated with reduced prostate cancer cell proliferation, whilst silencing of this tumour suppressor enhances proliferation and transformation." (PMID 28241429, 2017). "The two isoforms of PRUNE2::NTRK2 gene fusions identified in our study may, however, lead to modified or limited tumor suppressor function of PRUNE2 or even loss-of-function and consequently, a possible dominant-negative effect." (PMID 41323367, 2025). "This editing event ultimately leads to the suppression of PRUNE2 expression, highlighting the regulatory influence of NATs on oncogene or tumor suppressor function." (PMID 40507918, 2025). "Mechanistically, RANBP1 enhances miR-769-5p levels, promoting tumor growth and invasion by downregulating PRUNE2." (PMID 41186818, 2025). "Mechanistically, RANBP1 upregulates oncogenic miR-769-5p, which suppresses PRUNE2, a tumor suppressor that normally inhibits TNBC progression." (PMID 41186818, 2025). "Relative to controls, PRUNE2 expression was significantly lower in tumor (mean: –1.48; standard deviation: 0.92) than normal prostate (–0.78; 0.4, [p-value <0.001])." (PMID 36645410, 2023). "In 24 of these cases (22.4%), we extracted RNA from benign prostatic glandular tissue away from tumor (hereafter termed ‘normal prostate’: qRT-PCR was successful in all cases for PRUNE2 [n=24, 100%] and in most cases for PCA3 [n=21, 87.5%])." (PMID 36645410, 2023). "We next explored the association between biochemical recurrence and tumor expression levels of PRUNE2, PCA3, and the ratio of PRUNE2 to PCA3 expression by using several approaches." (PMID 36645410, 2023). "PRUNE2 protein is a tumor suppressor exerting various biological functions, including the suppression of Ras homolog family member A activity, which results in inhibition of oncogenic cellular transformation." (PMID 35282432, 2022). "PRUNE2 is a tumor suppressor in prostate and other cancers, inhibiting Ras homolog family member A (RhoA) activity to support oncogenic transformation." (PMID 36970726, 2022). "Other genes that were downregulated in RelC307X mice include Prune2, a tumour-suppressor gene with pro-apoptotic function." (PMID 34707143, 2021). "PCA3 is an antisense lncRNA transcribed from intron 6 of the PRUNE2 gene, which acts as a tumor suppressor in prostate cancer." (PMID 32928281, 2020). "The multi-functional BMCC1 (BCH motif-containing molecule at the carboxyl terminal region 1)/PRUNE2 plays a clear role in suppression of tumor activity." (PMID 31170959, 2019). "The PRUNE2 gene plays a role in cellular processes and is a potential tumor biomarker." (PMID 41323367, 2025). "PRUNE2 has a tumor suppressor function, but the function of PRUNE2 in the fusion protein is unknown." (PMID 41323367, 2025). "A reported germline PRUNE2 mutation and inactivation of the wild-type allele by LOH in the patient’s tumor indicates that PRUNE2 alterations might predispose to PC." (PMID 36900197, 2023). "In addition, PCa cells overexpressing PRUNE2 presented decreased cell adhesion, spreading and migration, while PCa cells in which PRUNE2 was stably silenced presented larger tumor xenografts." (PMID 31762940, 2019). "Therefore, PRUNE2 prevents oncogenic transformation of prostate cells and may control tumor growth through RhoA downregulation." (PMID 38896642, 2024). "Evidence is accumulating that PRUNE2 might act as a tumor suppressor gene." (PMID 36645410, 2023). "PRUNE2 (B-cell CLL/lymphoma 2 and adenovirus E1B 19 kDa interacting family) and CLU, encoding Clusterin a secreted chaperone, were also identified and have been shown to operate in cell death, cell transformation, tumour progression and neurodegenerative disorders." (PMID 35061738, 2022). "We compared the tumor gene expression of PCA3 and PRUNE2 to their corresponding expression in the normal prostate." (PMID 36645410, 2023).
tumor (continued). "Being located in the intronic antisense region of prune homolog 2 (PRUNE2) gene, PCA3 also modulates expression of this tumour suppressor." (PMID 28241429, 2017). "In this work we observed an overexpression of three specific glycosylation‐related genes, CHI3L1, KLRC3 and PRUNE2 in CSC from cancer cell lines and human primary tumour cells." (PMID 27641066, 2017). "The results showed downregulation of HOXD3, PRUNE2, CD302, CCDC8, and KLF2 (tumor vs. control)." (PMID 41186818, 2025). "The shortcoming of the study was the lack of tumor material; hence, the investigation of the biallelic inactivation of PRUNE2 in tumors was not achievable." (PMID 36900197, 2023). "Here, we assessed the tumor and control adjacent normal prostatic glandular tissue expression of the lncRNA PCA3 and the protein-coding PRUNE2 gene in two independent retrospective cohorts of patients with primary organ-confined prostate cancer after treatment by radical prostatectomy." (PMID 36645410, 2023). "The two nonsense mutations were predicted to produce a truncated PRUNE2 protein lacking the BCH domain and, thus, presumably losing the overall tumor suppressor functions, leading to loss of control over cellular transformation." (PMID 35282432, 2022). "The serum level of iPTH was correlated with serum Ca (p<0.001, rs=0.685), alkaline phosphatase (ALP) (p<0.001, rs=0.802), phosphorus (P) (p<0.001, rs=-0.525) and tumor diameter (p<0.001, rs=0.570), as well as the expression levels of VDR (p=0.009, rs=-0.403) and PRUNE2 (p=0.009, rs=0.401)." (PMID 34054720, 2021). "PCA3 can bind PRUNE2 pre-mRNA to form a PRUNE2/PCA3 dsRNA structure, which undergoes adenosine ADAR-dependent A-to-I RNA editing, leading to decreased expression of PRUNE2 and increased tumor cell proliferation." (PMID 32928281, 2020). "PRUNE2 and PCA3 elicited opposite effects on tumor growth in immunodeficient tumor-bearing mice." (PMID 26437436, 2015). "Tumor samples from the TCGA database had lower PRUNE2 expression than non-cancerous samples." (PMID 41186818, 2025). "Finally, we assess whether tumor expression levels of PCA3 and/or PRUNE2 are prognostic of biochemical disease recurrence after surgery." (PMID 36645410, 2023). "However, without additional studies, it is not possible to confirm whether the change in the last amino acids will affect the function of the BCH domain and the tumor suppressor function of the PRUNE2 protein." (PMID 41323367, 2025).
cancer (18 papers, 2011 to 2025). A tumor composed of atypical neoplastic, often pleomorphic cells that invade other tissues. "In our analysis, PRUNE2 is affected by four different, but consistently selected-against, alleles in four cancer types." (PMID 34059054, 2021). "Although NTRK-associated fusions are significant in various cancers and have led to the development of targeted therapies, such as larotrectinib and entrectinib, the specific molecular impact of atypical PRUNE2::NTRK2 fusion remains unclear." (PMID 41323367, 2025). "Increased PCA3 levels have also been found in other cancers such as choriocarcinoma as well as ovarian and thyroid cancer, indicating involvement of PRUNE2 in the pathogenesis of these cancers." (PMID 36900197, 2023). "Additionally, repression of PRUNE2, which participates in cancer, was detected in PMBCs exposed to permethrin." (PMID 37047231, 2023). "COL27A1, PRUNE2, MAEA, TBC1D3, GADD45B, ANXA8 and TSPY1 have been confirmed to play a pro‐resistant role in various cancers, which reflects the reliability of the hGeCKO library screening to some extent." (PMID 39550701, 2024). "Editing by ADAR1 at multiple sites in the PCA3/PRUNE2 duplex results in a reduction of PRUNE2, and an increase in PCA3 expression, therefore increasing in cancer cell the ability of cancer cell, such as proliferation, adhesion and migration." (PMID 35898396, 2022). "For RFS, those with cancer recurrence presented higher expression patterns of DDX11 and lower expressions of TMEM38B and PRUNE2, in both the univariate and multivariate analyses." (PMID 31963294, 2020). "The PCA3/PRUNE2 duplex undergoes A-to-I editing at multiple sites by ADAR1, which leads to reduced levels of PRUNE2, increased PCA3 expression levels and, thereby, a subsequent increase in cancer cell proliferation, adhesion and migration." (PMID 30585209, 2018). "Next, for PRUNE2 expression, PCA3 expression, and their ratio, we regrouped the cancer cases according to whether the values were greater than (deemed ‘high’) or less than/equal to (deemed ‘low’) their respective mean values." (PMID 36645410, 2023). "For CSS, patients with cancer-specific death presented higher expression patterns of RGPD8, BAIAP2L1, and DDX11 and lower expression patterns of SLC16A9, FRAS1, AQP1, TMEM38B, and PRUNE2, in both the univariate and multivariate analyses." (PMID 31963294, 2020). "PRUNE2 was previously studied in the central nervous system and in cancer patients, but there are no reports related to the function of PRUNE2 in the heart." (PMID 23741331, 2013). "Importantly, none of these top-5 genes in both level-2 (except PRUNE2) and level-3 are ever reported as biomarkers (over-expressed and/or under-expressed) for any type of cancer." (PMID 21909426, 2011). "Unlike PRUNE2 and CHI3L1 proteins, KLRC3 gene coding for NKG2E protein, has never been reported in cancer." (PMID 27641066, 2017).
heart diseases (1 paper, 2013). "All of these data suggest an important role for PRUNE2 in heart function and heart diseases." (PMID 23741331, 2013).
infection (1 paper, 2022). The state of being infected such as from the introduction of a foreign agent such as serum, vaccine, antigenic substance or organism. "SLIT2 and PRUNE2 represent infection-associated genes where expression was assessed as higher by RNA-seq in Holstein relative to Sahiwal infected cells." (PMID 35061738, 2022). "SLIT2, LITAF, PRUNE2 and genes involved in “Integrin signalling” showed altered numbers of TashAT2 motifs and, together with “PI3K/AKT signalling”, integrin signalling genes were significantly enriched by IPA in the Infection Associated-H/S data set." (PMID 35061738, 2022).
metabolic disorders (1 paper, 2025). "Meanwhile, SRRM2-AS1 and PRUNE2 represent understudied candidates with potential relevance to vascular or metabolic disorders, warranting further investigation." (PMID 40357364, 2025).
PRUNE2 also shares sentences with these, for which no sentence is quoted: prostate tumors (4 papers); colon cancers (2); melanoma (2); metastatic disease (2); adenoma (1); autism (1); Benign Parathyroid Neoplasms (1); blood pressure (1); breast carcinoma (1); cervical cancer (1); choriocarcinoma (1); dementia (1); glioma (1); hyperthyroidism (1); microdeletion syndrome (1); ovarian carcinoma (1); prostate (1); sarcoma (1); soft tissue sarcoma (1); triple-negative breast carcinoma (1).